OPN1MW (opsin 1, medium wave sensitive)
Description:
G protein-coupled photoreceptor that selectively activates G(i) proteins in response to medium-wavelength (green) light, thereby decreasing intracellular cAMP levels (PubMed:2937147, PubMed:6140680, Ref.6). Activation occurs when the opsin-bound cis-retinal chromophore absorbs a photon and isomerizes to all-trans-retinal, inducing a conformational change in the opsin that triggers a G protein-mediated phototransduction cascade (Ref.6). Mediates visual perception of green light in cone photoreceptor cells.
Synonyms: GOP; GCP; OPN1MW1; COD5; CBBM; CBD
Tractability: Small molecule: a structure with a bound ligand is known; it belongs to a druggable protein family. Antibody: UniProt places it where antibodies can reach, with high confidence; its Gene Ontology location is reachable by antibodies, with high confidence; UniProt predicts a signal peptide or a membrane-spanning region.
Gene: Protein-coding gene on chromosome X (154,182,596 to 154,196,861, forward strand). Ensembl gene ENSG00000268221.
Subcellular location: Cell membrane; Photoreceptor outer segment membrane
Pathways (Reactome):
Signal Transduction: G alpha (i) signalling events; Opsins
Disease: Defective visual phototransduction due to OPN1MW loss of function
Sensory Perception: The retinoid cycle in cones (daylight vision)
Gene Ontology:
Molecular function: identical protein binding; photoreceptor activity; G protein-coupled photoreceptor activity; G protein-coupled receptor activity
Biological process: absorption of visible light; positive regulation of cytokinesis; visual perception; cellular response to light stimulus; G protein-coupled receptor signaling pathway; phototransduction; transducin-mediated opsin signaling pathway
Cellular component: plasma membrane; cone photoreceptor disc membrane; photoreceptor disc membrane; photoreceptor outer segment; membrane
Gene-disease validity (ClinGen):
ClinGen rates the evidence that OPN1MW causes each of these diseases.
red-green color blindness (X-linked): Definitive. Deuteranopia is a type of color vision deficiency where the green photoreceptors are absent.
Homologues: Orthologues: chimpanzee OPN1LW (99% identical), macaque OPN1MW3 (98% identical), macaque OPN1LW (96% identical), dog OPN1LW (90% identical), rabbit OPN1MW (88% identical), rat Opn1mw (88% identical), guinea pig Opn1mw (81% identical), tropical clawed frog opn1lw (79% identical), mouse Opn1mw (79% identical), zebrafish opn1lw1 (76% identical), zebrafish opn1lw2 (76% identical). Paralogues in human: OPN1MW2 (100% identical), OPN1MW3 (100% identical), OPN1LW (96% identical), RHO (43% identical), OPN1SW (42% identical), OPN3 (26% identical), OPN4 (24% identical), RRH (23% identical), OPN5 (20% identical).
Diseases named in the same sentence as OPN1MW in open-access papers:
OPN1MW is named in the same sentence as 15 diseases in open-access papers, as found by Europe PMC text mining. Sharing a sentence is not in itself a finding about the gene and the disease. The quoted sentences say what the papers report.
blue cone monochromacy (8 papers, 2015 to 2025). Blue cone monochromatism (BCM) is a recessive X-linked disease characterized by severely impaired color discrimination, low visual acuity, nystagmus, and photophobia, due to dysfunction of the red (L) and green (M) cone photoreceptors. "Blue cone monochromacy (BCM) is an X-linked retinal disorder caused by mutations in the OPN1LW/OPN1MW gene locus, resulting in impaired cone function and structural degeneration." (PMID 40297680, 2025). "Blue cone monochromacy (BCM) is a congenital retinal disorder caused by mutations in the OPN1LW / OPN1MW gene cluster on the X chromosome that controls the expression of the red (L, long wavelength) and green (M, middle wavelength) cone photoreceptor opsins." (PMID 25909963, 2015). "Blue-cone monochromacy (BCM) is an X-linked recessive disorder caused by pathogenic variants in the OPN1LW and OPN1MW genes." (PMID 40364109, 2025). "Blue cone monochromacy (BCM) is characterized by loss of function of both OPN1LW (the first) and OPN1MW (the downstream) genes on the X chromosome." (PMID 30065301, 2018). "Blue cone monochromacy (BCM) is a rare X‐linked disorder characterised by a marked reduction or absence of L‐opsin and M‐opsin expression (encoded by the neighbouring OPN1LW and OPN1MW genes), impairing L‐ and M‐cone function." (PMID 40013354, 2025). "However, some genes have complex structures that are difficult to analyze, including the OPN1LW/OPN1MW gene cluster in blue cone monochromacy and the IKBKG/NEMO genes in incontinentia pigmenti." (PMID 39271608, 2024). "Blue cone monochromacy is characterized by attenuated or absent L-opsin and M-opsin expression encoded by OPN1LW and OPN1MW, and is strongly linked to high myopia." (PMID 40535564, 2025). "Among these IRDs is blue cone monochromacy (BCM), the X-linked congenital disorder with loss of red (L, long wavelength sensitive) and green (M, middle wavelength sensitive) cone photoreceptor function secondary to mutations in the OPN1LW/OPN1MW gene cluster on chromosome Xq28." (PMID 32848570, 2020).
retinitis pigmentosa (2 papers, 2020 to 2023). Retinitis pigmentosa (RP) is an inherited retinal dystrophy leading to progressive loss of the photoreceptors and retinal pigment epithelium and resulting in blindness usually after several decades. "The dCas9‐VPR system can be a therapeutic approach to treat Opn1mw (+) retinitis pigmentosa." (PMID 37356052, 2023). "As expected, expression levels for the cone-specific genes Opn1sw, Opn1mw, and Gnat2 in the Rds mutant retinas at P25 did not deviate from wild type levels since cone degeneration is delayed in this retinitis pigmentosa model." (PMID 32313077, 2020).
cone-rod dystrophy (1 paper, 2022). Inherited retinal dystrophies that belong to the group of pigmentary retinopathies. "Additionally, a mouse knockout model of BBS5 developed a cone-rod dystrophy as well as displayed mislocalization of cone-specific proteins such as OPN1SW, OPN1MW and GNAT2; we report that OPN1MW and GNAT2 are mislocalized in Bbs10−/− mice." (PMID 36125046, 2022).
Dyschromatopsia (1 paper, 2022). A form of colorblindness in which only two of the three fundamental colors can be distinguished due to a lack of one of the retinal cone pigments. "Certain combinations of common variants in exon 3 of OPN1LW and OPN1MW, the genes encoding the apo-protein of the long- and middle-wavelength sensitive cone photoreceptor visual pigments in humans, induce splicing defects and have been associated with dyschromatopsia and cone dysfunction syndromes." (PMID 35743313, 2022).
male infertility (1 paper, 2023). The inability of the male to effect fertilization of an ovum after a specified period of unprotected intercourse. "Moreover, we investigate the Y-chromosome genes, DAZ1/DAZ2/DAZ3/DAZ4, of which structural variants have been linked to male infertility, and X-chromosome genes OPN1LW and OPN1MW linked to eye disorders." (PMID 37365340, 2023).
myopia (1 paper, 2025). "Additionally, hemizygous variants in OPN1MW are associated with BCM, which is strongly associated with high myopia in males." (PMID 41153400, 2025).
retinal degeneration (1 paper, 2022). Degeneration of the retina. "The Opn1mw gene is essential for normal colour vision and it has been shown that its transactivation delays retinal degeneration and improves retinal function in the heterozygous rhodopsin-deficient (Rho+/−) RP mouse model." (PMID 35626712, 2022).
retinoblastoma (1 paper, 2022). A malignant tumor that originates in the nuclear layer of the retina. "Minigene splicing outcomes were similar in HEK293 cells and the human retinoblastoma cell line WERI-Rb1, the latter retaining a cone photoreceptor expression profile including endogenous OPN1LW and OPN1MW gene expression." (PMID 35743313, 2022).
Tritanopia (1 paper, 2023). Tritanopia is a very rare color vision disturbance in which there are only two cone pigments present and a total absence of blue retinal receptors. "Deuteranopic color blindness has been attributed to defects in OPN1MW gene, while tritanopia is attribute to mutations in OPN1SW47,48." (PMID 37069190, 2023).
OPN1MW also shares sentences with these, for which no sentence is quoted: autosomal recessive cone rod dystrophy (1 paper); cystic fibrosis (1); hearing loss (1); incontinentia pigmenti (1); insomnia (1); retinal tumors (1).